GZMB (granzyme B)
Diseases named in the same sentence as GZMB in open-access papers (continued):
Sharing a sentence is not in itself a finding about the gene and the disease.
infection (301 papers, 2008 to 2026). The state of being infected such as from the introduction of a foreign agent such as serum, vaccine, antigenic substance or organism. "The pronounced infiltration by CD8+ T cells and the close association of CD8+ T cells with neuronal cells and granzyme B+ cells with astrocytes are signs of a prominent cytotoxic response of the human immune system to the VSBV-1 infection." (PMID 31107210, 2019). "The reduction in the levels of Treg-associated molecules, such as Foxp3, CCR5, CCR6, PD-L1 and Granzyme B, maintained even after week 10 post-infection, corroborates the beneficial effects of the early anti-CD25 treatment." (PMID 26512987, 2015). "Consistently, Smad4 deficiency led to partially diminished GzmB expression in Kb-ova+CD8+ splenic T cells upon OVA peptide restimulation 5 days after the secondary infection." (PMID 26583325, 2015). "By contrast, viral loads in the livers of mice deficient in GzmB, either alone, or in combination with GzmA, were significantly higher than those observed in B6 mice at day 6 post-infection." (PMID 25502180, 2014). "Our findings demonstrate that polymorphisms in granzyme B can profoundly affect the outcome of infections with some viral pathogens." (PMID 25502180, 2014). "Thus, ex vivo ELISPOT measurements of granzyme B have been established as an “immune diagnostic” means of identifying effector responses to active infections." (PMID 33400687, 2021). "To determine the cytotoxic potential of CD38+ CD8+ T cells generated during P. vivax infection, we measured their intracellular expression of granzyme B and perforin by flow cytometry, in an independent cohort (n = 2 because of logistics associated with vivax experimental infection)." (PMID 27930660, 2016). "Therefore, production of granzyme B alone by DENV-NS3 specific T cells appeared to be associated with the occurrence of mild/subclinical infection." (PMID 25875020, 2015). "In wild mouse populations, variants of granzyme B have been identified, but how these function, especially in the context of infections, is unknown." (PMID 25502180, 2014). "Thus, neither inflammatory cytokine levels, compensatory changes in other granzymes, nor intestinal permeability could explain the reduced susceptibility of GzmB KO mice to infection." (PMID 39137883, 2024). "However, while cytotoxicity mediated by CD8+ T cells and Granzyme B have been associated with pathology in CL, IL-1β seems to have a dual effect as this cytokine may have a protective role in the early phase of the infection in mice." (PMID 32851099, 2020). "Using murine models, we found that infection induced a robust expansion of CD4 T-cells expressing granzyme B, perforin, and IFN-γ." (PMID 42206042, 2026). "In our experimental model, at the peak of infection (14 dpi), the vast majority of splenic granzyme B+ and perforin+ CD4+ T cells expressed CRTAM." (PMID 40590226, 2025). "In the macaque model of TB, CD8+ T cells expressing PRF1, GZMB, and GNLY were associated with protective granuloma and linked with protection from Mtb in the early stage of infection." (PMID 39836471, 2025). "In line with this, reduced pro-inflammatory CD4 and CD8 T cell responses and corresponding cytokines IFN-γ and GzmB were found in TRαGS mice upon infection." (PMID 41159501, 2025). "Enhances anti-CMV immunity, increases NK cell number, enhances IFN-γ and granzyme B expression, used in anti-infection therapy." (PMID 41568029, 2025). "In contrast, Class1 was dominated by viral-infection annotations and antigen presentation (e.g., HLA-DRB1/DQB1/C, CD74, CTLA4, GZMB, PRF1), consistent with HIV-associated immune activation." (PMID 41394852, 2025). "FoxP3+ cells accounted for less than 5% of the total CD4+ T cell population and exhibited negligible levels of granzyme B and perforin expression, indicating that Tregs are unlikely to mediate the expression of granzyme B and perforin during the infection." (PMID 40590226, 2025).
infection (continued). "Infection with T. cruzi expands a CD39+CD73–P2X7+ CD4+ T cell population expressing the granzyme B effector molecule." (PMID 40590226, 2025). "Upon examining the LCMV-specific CD4+ T cells at day 3 post s.c. infection, we noted an increase in the Tcf-1+ population coupled with a decrease in GzmB+ cells when IFN-γ was blocked." (PMID 40169810, 2025). "As before, OT1 Control or OT1 POSHfl/fl GzmB-Cre CD8 T cells were transferred into congenically marked hosts followed by VSV-OVA infection." (PMID 40672960, 2025). "Already at day one post-infection, high frequencies of IFNγ-, TNFα- and granzyme B (GrzB)-producing CD8+ T-cells were detectable reaching the maximum at day one or three post-infection before declining." (PMID 39472590, 2024). "The findings of the present study also indicate that there was an increase in granzyme B production in PBMCs of HVL cases after infection with cGLP LdCen1−/− parasites." (PMID 38918456, 2024). "Concerning the histological distribution, CD4+, GZMB+ and Foxp3+ cell counts were higher at the IF region compared to the GC (p˂0.0001) considering the whole cohort and each infection status analyzed separately (p˂0.05)." (PMID 38273012, 2024). "In this study, we explored the relative contributions of GzmA and GzmB in providing protection against infection at the intestinal barrier." (PMID 39137883, 2024). "Here, predominant GzmB-induced apoptosis is still sufficient to clear local infection, and through Casp7 cleavage, mediate extrusion of Salmonella infected epithelial cells, which together limit bacterial translocation." (PMID 39137883, 2024). "There was a notable and significant reduction in GzmB+RSV+CD8+ T cells suggesting that IL-1α acts on the recruitment of antigen-specific CD8+ T cells during infection." (PMID 38382577, 2024). "To test this, we depleted mice of neutrophils for the first 2 weeks of infection using anti-Ly6G antibody and assessed pimonidazole and GzmB expression in CD8+ T cells." (PMID 38833303, 2024). "When isolated at day 30 after transfer, CXCR6+ T cells isolated from livers after resolved infection and transferred into mice developing persistent infection lost GzmB expression." (PMID 38987588, 2024). "GzmB in the target cell cytoplasm cleaves and activates caspases inducing apoptosis, thus providing a powerful arm of cytocidal immune response during infection and disease." (PMID 38968186, 2024). "In rodent lung filarial infection, GzmB KO mice were more resistant to infection, whereas GzmA KO had increased worm burdens as compared to WT mice." (PMID 39137883, 2024). "In this purview, the presence of infection-associated proteins (GUSB, GZMB, LEAP2, LY6D) in estrus urine is interesting." (PMID 37104448, 2023). "Both IL-12 and IL-15 are known activators of NK cells, which control infection through the secretion of perforin and granzyme B and production of IFN-γ and TNF-α." (PMID 37261350, 2023). "Pathogen-associated specific CD8+T cells, which produce high levels of IL-2, IFN-γ, TNF-α, perforin, and granzyme B to regulate the infection, are essential for HCMV immunity." (PMID 36723437, 2023). "In general, CD8+ CM and EM T cells isolated from the spleen, axillary LNs, and mesenteric LNs stained significantly higher for the proliferation marker Ki67 and for granzyme B at 10 dpi when compared with tissues from prior to infection." (PMID 37983245, 2023). "Secondary infection also increased the frequency and expression level of granzyme B- and IFN-γ -producing TRM." (PMID 37809077, 2023). "The mice receiving activated CD8+ T cells also exhibited higher granzyme B expression by day 2 after infection." (PMID 36951943, 2023). "Compared with vector group, the productions of IFN-γ and Granzyme B were also declined in co-cultured media in CD73 cDNA infection group." (PMID 37770937, 2023). "For example, CD8+ T cells and NK cells use granzyme B independently from perforin to extravasate into the tissues and traffic to sites of infection in vivo." (PMID 37809077, 2023).
infection (continued). "They must be licensed to produce granzyme B in the context of infection, TCR or MR1-independent cytokine stimulation." (PMID 36085311, 2022). "In the burn-injured group there was a significant reduction in TCF1 expression in both endogenous CD8+ T cells and gBT.I cells at day 7 post-infection, and a significant reduction in GzmB expression in gBT.I cells." (PMID 35505970, 2022). "Changes in Vδ1+ T cells in patients who became CMV seropositive after transplantation were consistent with an infection-induced increase in the proportion of CD27lo/neg T-bet+ Eomes+ granzyme B+ Teffector cells." (PMID 35613583, 2022). "Given that infection with EBV stimulates an immune response that consists largely of CD8+ cytotoxic T cells, it is expected that the infection with EBV contributes to the observed difference in the expression of granzyme B between the two subtypes." (PMID 35327381, 2022). "miR-19b-3p regulates inflammation and infection by targeting many targets, including granzyme B, an activator of signaling and transcription 3, and PKNOX1." (PMID 35812737, 2022). "We also observed increased CD8+ T activation markers, such as NF-κB-p100, granzyme B, and Ki-67 during infection in CN10 (left)." (PMID 35447093, 2022). "CD103+ CD69+ CD8+ TRM cells produced IFN-γ and GzmB and these cells increased by day 4 post re-infection in the lung and airways." (PMID 35108347, 2022). "Specifically, we identified a unique population of CD4+/CD8+ double positive T cells (DP T cells) that upregulated inflammatory cytokines such as TNF-⍺ as well as Granzyme B over the course of infection." (PMID 34929014, 2021). "mRNA transcription levels of perforin and granzyme B (from day 6 on) were increased in the later phase of the infection in both groups." (PMID 34578316, 2021). "Residual MAIT cells in chronic HCV-infection showed an activated phenotype with high levels of granzyme B, HLA-DR, PD-1 and CD69 expression and granzyme B levels remain high after successful cure." (PMID 34951583, 2021). "In the later phase of the infection, starting from day 6 or 9, the mRNA transcription levels of perforin and granzyme B were increased in both groups, and IL-6 mRNA transcription levels were increased predominantly in the vaccinated cats." (PMID 34578316, 2021). "During infection with HSV-2, T cells from CXCR3-deficient mice exhibited impaired CD8+ T cell cytotoxicity and reduced expression of T-bet, IFN-γ, perforin and granzyme B." (PMID 32574175, 2020). "Higher production of IL-17A, IFN-γ, IL-10, IP-10, GM-CSF, sFasL, Granzyme A, Granzyme B, Granulysin, and Perforin following infection positively correlated with HIV replication." (PMID 33214610, 2020). "Levels of IFN-γ, granzyme b, and perforin in NK cells in the liver increased from 2 to 4 weeks post-infection, and decreased significantly from 6 to 10 weeks post-infection." (PMID 33330140, 2020). "After the initial infection, the presence of GzmB significantly reduced the intracellular growth of WT Lm toward the range of the CFU counts of the severely attenuated ΔLLO bacteria." (PMID 32151975, 2020). "Activation, measured by CD38 or granzyme B upregulation, increased during each infection in vivo whilst also in vitro MAIT cells upregulated CD69 and IFN-γ in the presence of virally-infected APCs." (PMID 32536923, 2020). "As observed in infections assays in the presence of purified GzmB, the impaired intracellular bacterial growth was not caused by enhanced death of the infected host cells that were unaffected by the presence of killer cells during the infection procedure." (PMID 32151975, 2020). "High frequencies of CTLs specific for both RhCMV epitopes expressed granzyme B, and granzyme B+ frequencies remained at similarly high levels during chronic SIVmac239 infection." (PMID 32922404, 2020).
infection (continued). "In chronic SIVmac239 infection, RhCMV-specific CTLs exhibited higher levels of granzyme B expression and polyfunctionality, and lower levels of exhaustion marker expression, than SIVmac239-specific CTLs." (PMID 32922404, 2020). "The frequency of GzmB+ effector CD8+ CD43+ T cells was enhanced at day 7 after infection in spleens and in BM of PD-1−/− and PD-L1−/− mice in comparison to WT mice." (PMID 30804928, 2019). "In parallel, CD107a and granzyme B were also reduced in NK cells when C/OTg mice progressed to persistent HCV1b infection." (PMID 30944315, 2019). "Infection of Haemophilus influenzae (NTHi) results in IL-12 and IL-7 synergistically controlling granzyme B by upregulating the IL-12 receptor in lung CD4+ and CD8+ T cells, which are used for increasing antibacterial response." (PMID 31915416, 2019). "Later, at day 12 and day 15 after infection, the numbers of effector cells producing GzmB in the spleen were reduced and were similar to the numbers of GzmB producing cells in WT mice." (PMID 30804928, 2019). "To examine the effect of metformin on γδ T cell function, we evaluated the production of cytokines and granzyme B in γδ T cells at 6, 12, and 18 d post-infection with P. yoelii 17XNL." (PMID 30619302, 2018). "In contrast to circulating memory T cells, TRM cells maintain expression of the cytotoxic mediator granzyme B at the protein level, which provides them with the potential to contain infection at early stages through the elimination of infected cells." (PMID 30131803, 2018). "Using murine experimental challenge with two strains of influenza A virus, we show that MAIT cells accumulate and are activated early in infection, with upregulation of CD25, CD69 and Granzyme B, peaking at 5 days post-infection." (PMID 30413689, 2018). "Intrinsic IL-27R signaling appeared to have no role in controlling NK cell frequency or function, as measured by expression of Tbet, IFN-γ, and granzyme B at day 1 after LCMV Cl13 infection." (PMID 29593047, 2018). "For this purpose, we infected WT mice intraperitoneally and analyzed the intracellular expression of gzmA and gzmB before and 6, 14, and 20 h after infection by flow cytometry." (PMID 28694562, 2017). "We determined the NK-intracellular levels of the lytic enzymes perforin, and granzyme-B in samples collected during the early-acute phase of infection by DENV-2 and/or CHIKV as well as in samples collected from healthy donors." (PMID 26938618, 2016). "We found that infecting B cells with EBV greatly amplified GzmB secretion in response to the same stimuli, but the expression was terminated once the infection had become latent." (PMID 26191409, 2015). "At day 3–4 after infection, GzmB levels decreased but the number of detectable NK cells increased and the net result was more potent m157-specific target clearance." (PMID 26720279, 2015). "To assess possible mechanisms of MyD88/TRIF/MAVS-independent resistance to RSV, we looked for indicators of antiviral activity and measured levels of IFN-γ and granzyme B in the airways (BAL fluid) at different time points after infection." (PMID 26688048, 2015). "Upregulation of GzmB appeared to be equivalent in both Ly49H+ and Ly49H- cells and did not require the presence of m157-expressing virus at 40 hours after infection." (PMID 26720279, 2015). "Secretion of perforin and granzyme B is one of the pathways through which γδ T-cells exert direct anti-infection response." (PMID 26161861, 2015). "At 60 days after AdOVA infection in mice, GzmB expression was exclusively found in GFP+ (CX3CR1+) memory OT-ICX3CR1-GFP T cells irrespective of their CD62L expression level." (PMID 26404698, 2015). "We also observed that T cell activation decreased at 22 days post-infection together with a strong decline of the Granzyme B-expressing CD4+ T cell population." (PMID 24367519, 2013).
infection (continued). "The significant decrease (p<0.01) of the Brucella bacterial load from 8 days post-infection onwards correlated with a very strong T cell response, a large Granzyme B-expressing CD4+ T cell population and a diminution of IFN-γ secretion." (PMID 24367519, 2013). "At 5 days post-infection, Granzyme B+CD4+ T cells up-regulated the adhesion molecule CD44, but expressed neither the co-stimulatory receptor CD27 nor the memory T cell marker CD127 (a subunit of interleukin-7 receptor-α)." (PMID 24367519, 2013). "Granzyme B production between the groups also followed a similar trend, but at notably reduced levels, to that seen in primary infection." (PMID 23483844, 2013). "Following acute i.v. flu infection, we found that both IFN-γ and granzyme B expression levels in NK cells from infected WT mice were increased compared to uninfected animals similar to the in vitro infection data at 8–12 hpi." (PMID 23300570, 2012). "Similar observations have been made for human CD8+ T cells, with both granzyme A and granzyme B expression decreasing from 60% 1 month after infection to 33% within 1 year after infection." (PMID 23230439, 2012). "Later in infection, particularly after 72 h of co-culture, γδ T cells produced markedly stronger granzyme B, RANTES, IFN-γ, and CD36 transcripts." (PMID 21765931, 2011). "At later time points after infection (∼72 h), γδ T cells enhanced expression of granzyme B, RANTES, and IFN-γ mRNAs." (PMID 21765931, 2011). "To be sure that IL-2Jc did not stimulate NK cells or NKT cells, we examined their expression of the activation markers CD69, GzmB and IFNγ, 24 hours after infection and treatment with IL-2Jc." (PMID 21170302, 2010). "We tested if ECTV infection of target cells interferes with the processes established in the LCMV system by using ECTV-immune ex vivo gzmB+ Tc cells on ECTV –infected MEF.BakxBax−/− or MEF.Casp3x7−/− targets." (PMID 19838298, 2009). "A number of additional genes that play important roles in the immune response to infection were also increased in expression in response to trypanosome infection (GZMB, LYZ, CYBB and NCR3)." (PMID 19409086, 2009). "In rVV-SIINFEKL infected mice, 40–60% of the OT-I CD8+ T cells were positive for Granzyme B during the first 2 weeks of infection." (PMID 19436710, 2009). "Similarly, GZMB was expressed at approximately the same level at 6 hours and 24 hours after infection in resister and LTBI L.8 cells." (PMID 39836471, 2025). "In third infection, the T cell response was primarily driven by activated innate-like T cells but their abundance was substantially reduced (compared with first infection) and the induction of granzyme B and perforin was suppressed." (PMID 40214640, 2025). "Additionally, granzyme B concentration in the BALF was increased with heterotypic infection compared with homotypic infection for WT and μMT mice." (PMID 40493422, 2025). "Furthermore, booster vaccination stimulated cytotoxic responses in infection-naïve participants, characterized by granzyme B production." (PMID 40213554, 2025). "Furthermore, we observed that the expression levels of granzyme A, granzyme B, perforin and granulysin in the indirect contact group were downregulated to varying degrees at 48 h post-infection." (PMID 40370406, 2025). "To address this, we performed an overnight stimulation with NS3 DENV peptides (matched to the serotype of infection) in the presence of anti-PD-1 and/or anti-PD-L1 blocking antibodies or an isotype control and measured cytokine production and GzmB/perforin production of CD4+ and CD8+ T-cells." (PMID 40595657, 2025). "Surprisingly, we found that in the absence of GzmB alone, mice were even less susceptible to infection that WT mice." (PMID 39137883, 2024).